MAP4K4 (mitogen-activated protein kinase kinase kinase kinase 4)
Diseases named in the same sentence as MAP4K4 in open-access papers (continued):
Sharing a sentence is not in itself a finding about the gene and the disease.
sarcoma (1 paper, 2023). A usually aggressive malignant neoplasm of the soft tissue or bone. "SRSF3 regulates multiple cancer-related genes, including EP300, DDX5, and MAP4K4, to increase the proliferation of sarcoma cells." (PMID 37558679, 2023).
Sepsis (1 paper, 2026). Sepsis is defined as life-threatening organ dysfunction caused by a dysregulated host response to infection. "Overall, these results demonstrate that FoxO1 enhances glycolysis in Tim4+ macrophages through MAP4K4 signaling, thereby driving pro-inflammatory responses in sepsis." (PMID 41362741, 2026).
steatosis (1 paper, 2022). Increased lipid within the cytoplasm of cells. "Notably, MAP4K4 levels were 2.7 ± 0.4-fold higher in participants with NAS≥5 (defines definite NASH; n=24) compared with participants with NAS≤4 (defines simple steatosis or borderline NASH; n=38)." (PMID 35679904, 2022).
stomach adenocarcinoma (1 paper, 2023). "The analysis of the TCGA dataset for stomach adenocarcinoma suggests that the mRNA expression of MAP4K4 is overexpressed in GC tumors compared to normal tissues, indicating that perhaps MAP4K4 has oncogenic features." (PMID 37190200, 2023).
Theileriosis (1 paper, 2014). "By demonstrating a mechanistic link of TNFα signaling to the established motility regulator MAP4K4, we provide an explanation for how TNFα expression contributes to Tropical Theileriosis pathogenesis and how TNFα production could be linked with the progression of tumors to invasive cancers." (PMID 24626571, 2014).
thyroid (1 paper, 2017). "The novel miR-TG regulates a gene belonging to the MAPK signaling pathway, MAP4K4, what additionally strengthens its implication in thyroid carcinogenesis." (PMID 28855631, 2017).
cancer (77 papers, 2013 to 2025). A tumor composed of atypical neoplastic, often pleomorphic cells that invade other tissues. "For example, MAP4K1 affects immune cell activation, whereas MAP4K4 is linked to cancer cell movement and growth." (PMID 41034525, 2025). "Collectively, these results imply that MAP4K4 is associated with cancer metastasis and poor prognosis." (PMID 36922678, 2023). "One approach that deserves experimental validation is to target mechano-transduction-associated genes like MAP4K4/6/7 kinases to improve DNA damage repair in CIN+ cancers, mitigating CIN in these cancer cells." (PMID 38067140, 2023). "Studies have shown that MAP4K4 broadly regulates various biological functions and is implicated in disorders leading to disease conditions and cancer." (PMID 37190200, 2023). "In this mini-review, we will discuss the available evidence underlying the role of MAP4K4 in cancer and the experimental data supporting its inhibition as a new therapeutic strategy." (PMID 37223681, 2023). "MAP4K4 is implicated in major diseases including cardiovascular/metabolic diseases, cancer, and diseases associated with neuronal degeneration." (PMID 34032269, 2021). "Bioinformatics analysis revealed MAP4K4, a well-known tumor oncogene associated with malignant progression in various carcinomas, to be a potential target of miR-98-5p." (PMID 29970191, 2018). "As MAP4K4 was previously shown to be overexpressed in multiple tumour cell lines and cancers, and also implicated in tumour cell invasiveness, we investigated its role in previously reported invasiveness of KSHV-infected endothelial cells." (PMID 24244164, 2013). "Besides its mainstay pro-survival role in various malignancies, MAP4K4 has been implicated in cancer-associated cachexia." (PMID 37190200, 2023). "Likewise MAP4K4 inhibitors are explored in different disease indications linked to inflammation and cancer." (PMID 30547786, 2018). "MAP4K4 is required for cancer cell migration and is associated with cancer metastasis." (PMID 28061846, 2017). "To this end, we believe that a better understanding of biological functions and underlying mechanisms of MAP4K4 in cancer could have far-reaching implications for new directions in cancer therapy." (PMID 27800153, 2016). "Therefore, MAP4K4 deregulation associates to different pathologies, including cancer." (PMID 37369604, 2023). "Genetic interference and gene expression analyses have implicated MAP4K4 activity in a plethora of cellular functions relevant for physiological and pathophysiological processes, including organ development, systemic inflammation, metabolic disorders and in particular cancer." (PMID 29796184, 2018). "MAP4K4 overexpression has been reported in various cancer types, including colorectal, gastric, pancreatic, lung, ovarian epithelial cancers and HCC3,55,56." (PMID 41034525, 2025). "By modulating these and other signaling pathways, MAP4K4 can contribute to aberrant cell growth and survival, promoting cancer progression." (PMID 39941781, 2025). "By modulating focal adhesion dynamics, MAP4K4 can promote cancer cell invasion and metastasis by enabling cells to detach from the primary tumor and migrate to distant sites." (PMID 39941781, 2025). "Mitogen-activated protein kinase kinase kinase kinase 4 (MAP4K4) has recently emerged as a promising therapeutic target in cancer." (PMID 38548749, 2024). "It has been reported that MAP4K4 not only promotes tumorigenesis and cancer metastasis but also mediates the Ras‐induced cellular senescence." (PMID 38383842, 2024). "Several studies have found that MAP4K4 is involved in the proliferation, migration, and invasion of cancer cells, as well as the inhibition of apoptosis." (PMID 38548749, 2024). "MAP4K4 has been investigated for its regulatory role in metabolic and inflammatory diseases and various cancers." (PMID 37190200, 2023).
cancer (continued). "The pharmacological inhibitors of MAP4K4 offer immense possibilities for targeting MAP4K4 in various diseases, including cancers in the clinical setting." (PMID 37190200, 2023). "Downregulation of MAP4K4 in cancer cell lines inhibits cell proliferation and cell growth, apoptosis induction, and migration and invasion." (PMID 36905477, 2023). "A review study suggests that the signalling pathways regulated by MAP4K4 are responsible for cancer progression." (PMID 36683274, 2023). "Here, we investigate the role of MAP4K4 in the regulation of the collective migration behavior of cancer cells, using the squamous epidermoid carcinoma cell line A431 as a model for cluster migration." (PMID 37369604, 2023). "MAP4K4 contributes to cancer development in many ways but primarily acts through three main axes: activation of cell proliferation pathways, alteration of cytoskeleton function, and impairment of anti-tumor immune responses." (PMID 37223681, 2023). "Similar to a few other cancer types, RNA interference of MAP4K4 also showed a promising effect in alleviating the invasiveness of cervical cancer cells." (PMID 38201504, 2023). "Emerging evidence strongly indicated that MAP4K4 play an important role in cancer and many other biological progresses." (PMID 36922678, 2023). "By regulating MAP4K4 expression and/or activation levels, cancer cell clusters can modulate their level of cohesion and thus the nature of their collective migration properties." (PMID 37369604, 2023). "In the progression of gastric cancer and NSCLC, MAP4K4 was found to promote cancer cell growth, apoptosis, and migration by regulating Notch and NF-κB signalling pathways." (PMID 36683274, 2023). "Despite the importance of MAP4K4 for cancer progression, little is known about its downstream direct targets." (PMID 37369604, 2023). "The overexpression of MAP4K4 has been reported in tumors compared to normal tissues in various cancers." (PMID 37190200, 2023). "Through regulating the downstream JNK signalling pathway, MAP4K4 promotes cancer cell proliferation, growth, and metastasis." (PMID 36683274, 2023). "MAP4K4 has been reported to play a critical role in cell migration, invasiveness, and adhesion in various types of cancers." (PMID 37190200, 2023). "The role of MAP4K4 in CRC has been established as that of a regulator of cancer cell proliferation in vitro and in vivo models." (PMID 37190200, 2023). "Further studies are needed to elucidate the efficacy of specific pharmacological MAP4K4 inhibition in cancer patients and to test the safety of its pharmacological blockade." (PMID 37223681, 2023). "In recent years, several studies have reported that MAP4K4 plays a role in the initiation and progression of cancer." (PMID 37223681, 2023). "To test if MAP4K4 is regulating focal adhesions disassembly in A431 carcinoma cells, we performed live imaging of the focal adhesion component paxillin fused to GFP." (PMID 37369604, 2023). "Our work indicates that MAP4K4 is a key regulator of force balance to promote the collective migration of carcinoma cells." (PMID 37369604, 2023). "Using A431 carcinoma cells, we identify the kinase MAP4K4 as a central regulator of collective migration." (PMID 37369604, 2023). "Here, we found that MAP4K4, in the collective context, also induces focal adhesion turnover predominantly through moesin phosphorylation in A431 carcinoma cells." (PMID 37369604, 2023). "Using A431 carcinoma cells, the study shows that MAP4K4 coordinates cluster migration by regulating forces and stability of focal adhesions and adherens junctions, promoting cytoskeleton rearrangements." (PMID 37369604, 2023). "Detailed reviews of MAP4K4 control of cytoskeleton regulation and cancer can be found in references and, respectively." (PMID 36568222, 2022). "Previous studies have shown that MAP4K4 plays multiple roles in cancer metastasis, and MAP4K4 can promote oncogenic transformation by regulating its downstream targets." (PMID 36292671, 2022).
cancer (continued). "Consistently, studies in cell lines and animal models have revealed that MAP4K4 aggravates the migration and invasiveness of different types of cancer cells including breast, prostate, and ovarian cancer, malignant melanoma, glioblastoma, as well as HCC." (PMID 35679904, 2022). "The implication of MAP4K4 in the regulation of cytoskeleton dynamics and cell motility provided essential insights into its role as a pro-metastatic kinase in cancer." (PMID 36568222, 2022). "MAP4K4 is critically involved in regulating cell-autonomous tumor growth and cancer metastasis (see also chapters 3.3 and 3.4)." (PMID 36568222, 2022). "As for many emerging kinase targets, small molecule inhibitors of MAP4K4 have been developed and their anti-cancer activities explored." (PMID 36568222, 2022). "Another remarkable finding in the cancer field is the anti-proliferative activity of MAP4K4 through the activation of Hippo tumor suppressor signaling." (PMID 36568222, 2022). "In cancer cells, downregulation of MAP4K4 increases apoptosis and cell cycle arrest and inhibits cell proliferation." (PMID 36497065, 2022). "A better understanding of these mechanisms is particularly relevant in the brain, where MAP4K4 is highly expressed and under pathological conditions either drives neuronal cell death in neurodegenerative diseases or cell dissemination in malignant tumors." (PMID 36568222, 2022). "MAP4K4 was identified as a broadly overexpressed kinase in human tumor cells and has since then been recognized as an emerging target in cancer, in particular in solid tumors of epithelial tissues." (PMID 36568222, 2022). "MAP4K4 is significantly upregulated in numerous cancer cell lines and tumors relative to their normal counterparts." (PMID 35538031, 2022). "MAP4K4 interaction with STRN4 was also proposed to promote malignant characteristics of cancer cells." (PMID 35941177, 2022). "According to a recent study, mitogen-activated protein kinase isoform 4 (MAP4K4) is majorly involved in cancer cell growth." (PMID 36292671, 2022). "It competitively binds to miR-141-3p which can target Mitogen-Activated Protein Kinase Kinase Kinase Kinase 4 (MAP4K4) to influence cancer progression." (PMID 35662010, 2022). "MAP4K4 is regarded as an important kinase regulating inflammatory pathways and has been reported to play roles in cancer." (PMID 34511598, 2021). "The results revealed that SOX9, RASA1, CEP55, and MAP4K4 were significantly higher expressed in LUAD tissues than those in adjacent cancer tissues." (PMID 33510968, 2021). "The oncogenic functions of MAP4K4 have been described in a variety of tumors, and selective inhibitors are being tested for cancer treatment." (PMID 35083135, 2021). "MAP4K4 is emerging as a key regulatory kinase involved in the development of major diseases in society including cardiovascular disease and cancer." (PMID 34032269, 2021). "Nonetheless, we show that MAP4K4 is required for efficient cell proliferation in several different MEK/ERK inhibitor resistant cancer cell lines, uncovering a potential new therapeutic target." (PMID 33924486, 2021). "In cancer cells, MAP4K4 interacts directly with Strn4 and disruption of the complex results in oncogenic transformation." (PMID 34032269, 2021). "MAP4K4 is a Ste20 member and reported to play important roles in various pathologies, including in cancer." (PMID 34511598, 2021). "This influence of MAP4K4 on cell adhesion and migration has clear implications for cancer and blood vessel permeability." (PMID 34032269, 2021). "It was reported that alternatively spliced MAP4K4 variants showed differential influences on the EMT process, which is a critical process for the migration and invasion of cancer cells." (PMID 33072610, 2020).
cancer (continued). "Lung tumor cells prefers to use the shorten length transcripts of FGF2 (A) and MAP4K4 (B) compared to para-cancer tissue cells, and knocking-down of CSTF2 expression in H460 cells leads to extended length of transcripts for both FGF2 and MAP4K4 genes." (PMID 31391087, 2019). "Although emerging evidence suggests that MAP4K4 is involved in many aspects of cell functions and processes, information regarding MAP4K4 in different types of cancer is very limited." (PMID 28306189, 2017). "Regardless of the detailed underlying mechanism, it appears that downstream signaling selection by MAP4K4 and how MAP4K4 activates its target are cell type‐, cancer type‐, or context‐specific." (PMID 28306189, 2017). "Identification of direct substrates of MAP4K4 will provide crucial clues as to how MAP4K4 is mechanistically involved in cancer." (PMID 27800153, 2016). "Detailed molecular understanding of how MAP4K4 is involved in cancer biology is essential for firmly establishing MAP4K4 as a target for that particular type of cancer." (PMID 27800153, 2016). "In this review, we will discuss current understanding of MAP4K4 regulation and summarize evidence that implicates MAP4K4 in cancer." (PMID 27800153, 2016). "Current evidence supports but not yet provides sufficient biological and mechanistic justification for MAP4K4 as a novel cancer therapeutic target." (PMID 27800153, 2016). "In cancer cells, in general, downregulation of MAP4K4 results in induction of apoptosis, cell cycle arrest and inhibition of cell growth and proliferation, migration and invasion." (PMID 27800153, 2016). "If MAP4K4 contributes to cancer development and progression, it is highly likely that MAP4K4 can also be involved in treatment resistance." (PMID 27800153, 2016). "The first evidence suggesting a role of MAP4K4 in cancer came from observations that MAP4K4 is highly expressed in 40 of the NCI-60 human tumor cell lines and can modulate cellular transformation, adhesion and invasion." (PMID 27800153, 2016). "Since MAP4K4 controls inflammatory signaling pathways downstream of TNFα and cancer cell motility, we investigated MAP4K4 functions in macrophages infected with T. annulata, which display a parasite-dependent chronic increase in TNFα expression." (PMID 24626571, 2014). "In parallel, unrelated studies a still unclear picture of MAP4K4 functions in cancer progression began to emerge, where MAP4K4 was identified in genetic interference screens as promoter of cell motility and invasiveness." (PMID 24626571, 2014). "We discuss here the relevance of TNFα-MAP4K4 signaling forpathogen-driven cell dissemination and its potential impact on the induction ofmetastasis in human cancer." (PMID 28357238, 2014). "Furthermore, MAP4K4 plays a significant role in cancer metastasis, particularly through its involvement in the regulation of collective cell migration." (PMID 41034525, 2025). "This could suggest that suppression of IKK1/α could possibly halt other pathways due to its wide array of interaction with other proteins, such as IKK2/β, AKT1, MAP4K4, and TRAF2, that are possibly implicated with other cancer pathways." (PMID 39062574, 2024). "MAP4K4 was shown to be involved with FA disassembly; STRIP1 deficient MEFs exhibited reduced number of FA with increase in their clustering; and depletion of CCM3 in cancer-associated fibroblasts increased the size and number of FA per cell." (PMID 39417621, 2024). "More recently, MAP4K4 has emerged as a promising therapeutic target in cancer." (PMID 38548749, 2024). "More and more information regarding MAP4K4’s role in cancers had been reported." (PMID 36922678, 2023). "Studies published over the last five years have shown that MAP4K4 plays a role in the initiation and progression of cancer, primarily by activating intracellular proliferative signaling (such as the JNK and MLK3 pathways), impairing cytoskeleton function, and reducing anti-tumor immune responses." (PMID 37223681, 2023).